RNU6-1066P (RNA, U6 small nuclear 1066, pseudogene)
Gene: Small nuclear RNA gene on chromosome 22 (27,035,887 to 27,035,991, forward strand). Ensembl gene ENSG00000200443.
Homologues: Orthologues: chimpanzee U6 (98% identical), macaque U6 (90% identical), dog U6 (70% identical), guinea pig U6 (64% identical). Paralogues in human: RNU6-1152P (76% identical), RNU6-1075P (75% identical), RNU6-44P (75% identical), RNU6-1060P (74% identical), RNU6-1243P (74% identical), RNU6-166P (74% identical), RNU6-41P (74% identical), RNU6-589P (74% identical), RNU6-637P (74% identical), RNU6-643P (74% identical), RNU6-655P (74% identical), RNU6-797P (74% identical), and 1286 more.